STAT3 (signal transducer and activator of transcription 3)
Diseases named in the same sentence as STAT3 in open-access papers (continued):
Sharing a sentence is not in itself a finding about the gene and the disease.
tumor (continued). "In the present study, we investigated the existence of a correlation between active STAT3 and physical state as well as the copy number of viral genome in HPV16 positive tumor tissues from cervical precancer and cancer lesions." (PMID 31487312, 2019). "Using patient-derived xenograft mice models in which the heterogeneity of the primary human tumor was preserved, we found that simultaneous blockade of YAP1 and STAT3 by verteporfin suppressed CSC activity and tumor growth when combined with chemotherapy." (PMID 31137841, 2019). "Taken together, the results demonstrated that miR-126 exerts tumor suppressing effects on the proliferation, migration and invasion by inhibiting MMP2, MMP9 and JAK2/STAT3 pathway via targeting ZEB1." (PMID 31007650, 2019). "The proteomic tumor signatures revealed increased levels of STAT3, which can become activated by ERBB receptor tyrosine kinase signaling, as well as an enrichment of STAT3 target genes." (PMID 30645971, 2019). "Extract from cinnamon was a potent inhibitor of VEGF secretion, inhibited the expression and phosphorylation of STAT3 and AKT, suppressed HIF1α expression as well as significantly reduced tumor growth and blood vessel formation in mice models." (PMID 31861720, 2019). "We envisage that this autocrine mechanism can contribute in part to STAT3 activation, since both AZD1480 and Linsitinib dual targeting conferred a significant mitigation of tumor cell growth and proliferation." (PMID 31399589, 2019). "STAT family members notably STAT3 and STAT5 have been involved in cancer progression whereas STAT1 plays opposite role by suppressing tumor growth." (PMID 30847297, 2019). "In this study, we found that RAF inhibitor (AZ628) combined with STAT3 inhibitor (BP-1-102) reversed this little efficacy, and had a great effect on suppressing the growth of KRAS mutant cancer cells and tumor." (PMID 31484165, 2019). "STAT3 can be activated by IL-6 and its persistent activation contributes to CRC tumor growth and proliferation." (PMID 31864341, 2019). "In line with this, DFTD tumor cells expressed higher levels of TRIM28 compared with fibroblasts, and blockade of either ERBB signaling or STAT3 led to reduced transcription of TRIM28." (PMID 30645971, 2019). "STAT3 and STAT5 promote tumor progression by regulating the expression of cell cycle, survival and pro-inflammatory genes." (PMID 31557897, 2019). "Downstream targets of STAT3, among which matrix metalloproteinase 2 (MMP2) is also differentially modulated in the tumor biopsies." (PMID 30645971, 2019). "Various preclinical studies highlighted the effects of CUR on NF-kB, STAT3, COX2, and CXCL-1 (chemokine [C-X-C motif] ligand 1) activity, leading to reduced inflammation and eventually also impacting tumor progression." (PMID 31013694, 2019). "An examination of STAT protein expression levels showed that STAT6 levels were significantly lower in GSCs compared with non-tumor tissue, whereas levels of STAT1, STAT3 and STAT5 were significantly higher." (PMID 31530290, 2019). "It is demonstrated that CCL2 induces EMT process dependent on the activation of STAT3 signal and p-STAT3 inhibition suppresses CCL2 expression, leading to reduced invasiveness of tumor cells." (PMID 31182136, 2019). "Among them, signal transducer and activator of transcription 3 (STAT3) represents a crucial transcription factor for cell proliferation, survival and tumor development." (PMID 31581535, 2019). "Our results showed that miR-1224 suppressed tumor metastasis by directly targeting focal adhesion kinase (FAK) in intestinal-type GC and inhibiting the STAT3 and NF-κB signaling pathway, and subsequent epithelial-to-mesenchymal transition (EMT)." (PMID 31019895, 2019). "Playing key roles in chronic inflammation and tumor initiation, cytokines such as TNF, IL-1, and IL-6 and activated transcription factors like NF-κB and STAT3 control the main pro-tumorigenic signaling, which induces cellular transformation and malignancy." (PMID 30862050, 2019).
tumor (continued). "Given to NPC is an inflammation-related cancer, LPLUNC1 and PHB1 function in anti-tumour and anti-inflammation, and we demonstrated that LPLUNC1 inhibited NPC growth by suppressing the Stat3 pathway." (PMID 30886235, 2019). "Another example is a cyclic oligonucleotide decoy that corresponds to the STAT-3 response element of STAT-3-targeted genes, which showed promising anti-tumor efficacy in NSCLC models." (PMID 31417869, 2019). "The increased binds of CXCL1 or CXCL2 to CXCR2 leads to reduced SAP18 expression under tumor conditions, which subsequently activates the ERK/STAT3 signaling pathway to promote mo-MDSCs accumulation." (PMID 31395859, 2019). "Upregulation of the expression of p-Stat3, p-Akt and EMT markers, which have been reported to be characteristics of sorafenib resistance, was observed in the SR tumours." (PMID 31754201, 2019). "Similar to our findings in tumor cell lines, IFN-g preferentially activated STAT1 in Monos, while IL-27 activated both STAT1 and STAT3; IL-10 preferentially activated STAT3." (PMID 31730010, 2019). "inhibited the expressions of p-Stat3 and MMP-9, which are generally acknowledged to be correlated positively with tumor metastasis." (PMID 31649548, 2019). "Myricetin inhibits cell proliferation, tumor metastasis, angiogenesis, and induces cell death by inhibiting cancer signaling pathways such as MAPK, AP-1/cyclin D1, JAK-dependent STAT3 in various cancer cell lines." (PMID 31100782, 2019). "Interleukin 6 has also been shown to play key functions in multidrug resistance via JAK, STAT3, PI3K/Akt, and Ras-MAPK signal pathways, tumor cell migration, invasion, and other pathways of carcinogenesis." (PMID 31572184, 2019). "Another crude extract from the fruits of Rhus coriaria was also discovered to inhibit angiogenesis, tumor growth and metastasis in TNBC models in vitro and in vivo by repressing STAT3 phosphorylation and STAT3-mediated VEGF expression." (PMID 31088482, 2019). "IL-6 subsequently led to STAT3 activation and MMP9 expression in tumor cells, enabling increased metastatic invasion." (PMID 31921140, 2019). "When they genetically eliminated STAT3 in mouse lung tumors and human LUAD cell line A549, they found increased tumor growth, higher tumor grade, increased vascularization, and significantly reduced survival." (PMID 32039025, 2019). "US28 promotes angiogenesis and tumor formation via COX-2 induced production of IL-6, phosphorylation of STAT-3, and activation of nuclear factor-kappaB." (PMID 31203442, 2019). "Constitutive activation of STAT3 can result from IL-6, which is produced by MCL cells or cells in tumor microenvironment." (PMID 31861597, 2019). "To explore the mechanism by which apigenin regulated Noxa expression and synergized with ABT-263 to inhibit EGFRm tumor cells, we analyzed the phosphorylation status of EGFR and its downstream signalling pathways, including MAPK, PI3K-AKT and STAT3." (PMID 31367332, 2019). "Expecting differences, we were surprised of finding similar or higher expression of Stat3 and Arginase-I in Sparc−/− MDSC (both from spleen and tumor)." (PMID 31281314, 2019). "Blockade of IL-6/STAT3 signaling attenuated the expression of CD44, CSC-like properties, and aggressive tumor behavior in vitro and in vivo." (PMID 31315262, 2019). "In neoplasms, inordinate NF-κB promote the expression of many vital modulators of cancer progression, such as HIF-1α, AP-1, STAT3, and MUC1." (PMID 31781219, 2019). "STAT3, a member of the JAK/STAT signaling pathway downstream from IL6/8, is highly expressed in TNBC and connected with tumor initiation, aggressive clinical behavior, unfavorable outcome, and resistance to chemotherapy." (PMID 31443516, 2019). "It regulates tumor cells proliferation and invasiveness through MAPK, PTEN/AKT, and STAT3 signaling pathways." (PMID 31165412, 2019).
tumor (continued). "Recently, G9a has been demonstrated to interact with several transcriptional factors, including GATA3 and ZEB2, STAT3, and MYC, leading to the repression of gene transcription, while enhancing tumor survival." (PMID 31619200, 2019). "DC-SIGN contributes to the release of IL-10 that would maintain STAT3 activation in tumor cells, thus implying that DC-SIGN favors the maintenance of an activated STAT3 context in the tumor stroma." (PMID 31480382, 2019). "Phosphorylation of key tumor signaling pathways ERK and STAT3 was seen, in line with data on IL-21 signaling pathways in other cells, e.g., lymphocytes." (PMID 31540511, 2019). "Many oncogenic and tumor suppressive factors, such as Agrin, Rab7, AKT/mTOR pathway, STAT3, and transcription-3 signalling have been identified for HCC." (PMID 31164410, 2019). "Accordingly, a combined treatment consisting of PI3K and STAT3 inhibitors resulted in maximal suppression of T-ALL cell proliferation and tumor progression in vivo." (PMID 31064074, 2019). "Conversely, the inhibition of STAT3 activity using STAT3 inhibitors elevates the level of chemoattractant chemokines, including CCL2, CCL9, CCL12, and CCL17, and enhances tumor cell sensitivity to NK-mediated lysis." (PMID 31658669, 2019). "The results indicated that EGFR, AKT, STAT3, and EZH2 all play a crucial role in promoting cell proliferation and tumor growth in seminal vesicles of TRAMP mice." (PMID 31592235, 2019). "This novel drug disrupted STAT3 DNA binding activity in the nanomolar range and also slowed the growth of MDA-MB-468 tumor xenografts." (PMID 31671769, 2019). "This is surprising, since STAT3 has widely been described as a tumor driver in ALCL and STAT1 has been often ascribed a tumor suppressive function by inducing cell cycle arrest, apoptosis and suppression of metastasis." (PMID 30131584, 2019). "The increased levels of the IL-22 producing (Th22) cells were also observed in normal, paratumor, and tumor tissues from patients with TNBC, which confirmed the importance of IL-22/JAK/STAT3/MAPKs/AKT in metastasis of this disease." (PMID 31088482, 2019). "HGF induced activation of MET also triggers AKT or STAT3, induces epithelial–mesenchymal transition (EMT), and promotes multiple pro-tumor effects." (PMID 31367190, 2019). "After being able to differentiate between tumor- and TME-specific STAT3 activity, we next evaluated if this distinction has prognostic relevance." (PMID 31796877, 2019). "The fact that STAT3 is critically involved in the VEGF pathway and tumor angiogenesis indicates that blockade of STAT3 is a therapeutic target to heighten an effective antiangiogenic treatment in EOC." (PMID 31861720, 2019). "We utilized immunohistochemical staining to determine the expression and localization of STAT3, p-Stat3, and COX-2 in tumor cells." (PMID 31191326, 2019). "Among them, HO-3867 is the most studied and effective in selectively targeting STAT3 and inhibiting EOC tumor growth." (PMID 31861720, 2019). "(D) Liver tumor lysates were analyzed for the activation of JNK, ERK, p38, p65, and STAT3 by Western blotting." (PMID 30990169, 2019). "In support, our immunohistochemical staining of a GBM cohort (n = 45) showed an estimated 5.3-fold (p < 0.001) elevation in STAT3 and STAT5A protein expression in primary and recurrent GBM versus the non-tumor group." (PMID 31783691, 2019). "Compared with the shRNA control, TRIM59 knockdown decreased expression of p-STAT3, proliferation marker Ki-67, and cancer cell stemness marker CD44, whereas the levels of mH2A1 was elevated in GSC xenograft tumor tissues by immunohistochemical (IHC) analyses." (PMID 31488827, 2019). "TNF-α produced by tumor cells induces CD45RA−CCR7−Treg subset and inhibits their HLA-DR expression by phosphorylation and activation of STAT3." (PMID 31024835, 2019).
tumor (continued). "The main factors that correlate with the embryonic mesenchymal state, tumor metastases and progression include HLA-G, HSP70, hypoxia, STAT3, CD44, SNAIL1, TWIST1, PRRX1, TGFb, WNT/bCAT, ID, and MMPs." (PMID 30899759, 2019). "Stattic treatment reduced STAT3 phosphorylation, strongly downregulated LC3-II expression, especially at the higher dosage, and significantly inhibited tumor growth." (PMID 31311917, 2019). "Because of its role in the activation of the STAT3 signaling pathway, OSM participates in the regulation of the tumor immune microenvironment." (PMID 31871447, 2019). "Sustained IL-22 elevation and subsequent STAT3 activation were found with up-regulation of downstream genes in HCC mouse models, promoting tumor development and metastasis." (PMID 30824840, 2019). "The expression levels of SIRT3 were lower in the cancer patient tissues but higher in normal tissues, while the expression levels of STAT3, HIF‐1α, GLUT1, LDHA, and HK2 were higher in tumor tissues but lower in normal tissues." (PMID 30094960, 2018). "STAT3 inhibition and TLR9 immunostimulation disrupt the tolerogenic effects of the tumor microenvironment and thereby lead to potent antitumor immune responses in a variety of preclinical tumor models in mice." (PMID 29921770, 2018). "Conversely, a decrease in STAT3 signaling can enable MDSC differentiation into TAMs, which often become the dominant tumor-infiltrating myeloid cell population." (PMID 29921770, 2018). "Signal transducer and activator of transcription proteins 3 (STAT3), a member of STAT family, is well demonstrated to exerts an important effect on tumorigenesis and tumor-related inflammation." (PMID 29423040, 2018). "The results of this study suggest that the expression of MMPs in tumor cells is regulated by cell density through the synergistic paracrine mechanism of IL-6 and IL-8 via the JAK2/STAT3 signaling pathway." (PMID 30220965, 2018). "Two recently developed small-molecule STAT3 inhibitors, SC-43 and SC-78, which can stimulate SHP-1 to inactivate STAT3, were found to have anti-tumor activity." (PMID 30109144, 2018). "Here, we investigated the effect of the in vitro tumor microenvironment (TME) comprised of a 3D ECM and stromal cells (astrocytes and endothelial cells) on the migration and response to STAT3 inhibition in various GBM cell lines." (PMID 29566069, 2018). "We then detected the protein expression of p-STAT3 and p-JAK2 in the different tumor groups by immunohistochemical staining." (PMID 29693005, 2018). "Most importantly, ERO1α knockdown significantly repressed the death of HCC xenograft mouse models by reducing tumor distant metastasis, and host angiogenesis by suppressing the expression of S1PR1, p-STAT3, and VEGF-A in HCC cells." (PMID 30377291, 2018). "TFRG also markedly reduced tumor mass of MDA-MB-231 xenografts with inhibition of iNOS and formation of nitrotyrosine by JAK2/STAT3 signaling pathway." (PMID 29951107, 2018). "IL6R is bound by its IL-6 ligand and can activate downstream signaling pathways, such as MAPK, PI3K, and signal transducer and activator of transcription 3 (STAT3), which promotes tumor cell proliferation." (PMID 29626935, 2018). "In fact, blockade of IL-6 trans signaling by the designer cytokine sGP130Fc prevents tumor proliferation and angiogenesis in HCC at least in part via its inhibitory action on Stat3." (PMID 30224299, 2018). "STAT3, Notch1/2, Cullin1, TGF-B2, and CREBBP mediate tumor cell proliferation and therapeutic resistance, and inhibition of the Notch and TGF families sensitizes cancer cells to radiation therapy." (PMID 30546829, 2018).
tumor (continued). "FDTN contributed to the downregulation of the JAK2/STAT3 signaling pathway, and thus reversed the ELTN resistance to enable enhanced anti-tumor efficacy both in vitro and in vivo." (PMID 30483119, 2018). "The resveratrol-treated tumour tissues showed less Ki67 labelling, widely distributed apoptotic regions, upregulated PIAS3 expression and reduced p-STAT3 nuclear translocation." (PMID 30176837, 2018). "Tumor tissue samples were collected from 48 patients with GBM and were used to assess the relationship between miR-519a and STAT3 expression." (PMID 29843746, 2018). "In xenograft tumor model, tumor volume was significantly reduced by intraperitoneal injection of pantoprazole, with upregulation of SHP-1 and downregulation of p-STAT3, which were attenuated by concomitant injection of pervanadate." (PMID 30202514, 2018). "We also previously demonstrated that tumor angiogenesis of B16 required DR6, which was via the nuclear factor‐κB, P38 MAPK, and signal transducer and activator of transcription 3 (STAT3) pathways." (PMID 30186750, 2018). "Altogether, these and other studies support the participation of the NFκB and STAT3 pathways in the induction of an EMT- and stem cell-like phenotype that contributes to the tumor aggressive features." (PMID 29928478, 2018). "Given that SHP2 is primarily known to promote cancer, it seems counter-intuitive that it would function to dephosphorylate STAT3; however, some studies have revealed that SHP2 shows some tumor suppressive capabilities through its inactivation of STAT3." (PMID 30208623, 2018). "c-MET signaling in the presence of its ligand HGF controls tumor growth and invasiveness by activating MAPK/ERK cascades, PI3K/Akt axis, STAT3 pathway, and/or NF-κB inhibitor-α kinase (IKK)—NF-κB complex." (PMID 29670046, 2018). "Combined treatment with paclitaxel and momelotinib inhibited paclitaxel-induced JAK2/STAT3 activation and CSC-like development in mice xenografts, and consequently reduced the tumor burden significantly greater than that achieved by paclitaxel-treatment alone." (PMID 29682172, 2018). "This dual activation of the JAKs/STAT3 cascade can play a pivotal role in tumor progression, and blockade of the JAK/STAT3 signal by OP-D can provide an important therapeutic strategy." (PMID 30413072, 2018). "We also observed that OP-D was effective in suppressing the expression of STAT3, JAK1, JAK2, and Src phosphorylation in tumor tissues." (PMID 30413072, 2018). "Collectively, our findings support the notion that G3BP1 promotes tumor progression and metastasis through IL-6/G3BP1/STAT3 signaling axis in RCC." (PMID 29717134, 2018). "Additionally, in one of the patients with a STAT3 mutation, we detected a 9p copy number gain containing JAK2 and a point mutation in the protein tyrosine phosphatase (PTP) PTPRK, a commonly deleted tumor suppressor shown to negatively regulate STAT3 in NKTCL19." (PMID 29674644, 2018). "In T-cell lymphomas such as primary cutaneous T-cell lymphomas (CTCL) and anaplastic large T-cell lymphoma (ALCL), both STAT3 and STAT5 are deregulated, and the targeting these two proteins can inhibit tumor pathogenesis in vitro." (PMID 30217007, 2018). "Considerable evidence has demonstrated an essential role for STAT3 in the regulation of genes such as SOCS3, cyclin D1 and HIF1α in promoting tumor cell proliferation, migration, invasion and resistance to therapies." (PMID 30572654, 2018). "Several parallel studies showed that GPRC5A exerts its tumor suppressive effect by regulating the NF-κB and EGFR/STAT3 signaling pathways." (PMID 30417009, 2018). "Here we provide the first evidence of a molecular mechanism for GLE anti-tumor action, demonstrating that it inhibits BCSCs by inhibiting the JAK2/STAT3 pathway and BCSC survival signaling." (PMID 30542507, 2018).